AR (androgen receptor)
Diseases named in the same sentence as AR in open-access papers (continued):
Sharing a sentence is not in itself a finding about the gene and the disease.
breast carcinoma (continued). "The activated androgen receptor (AR) has recently been shown to promote EMT activation via suppression of E-cadherin expression within breast cancer cells." (PMID 25409297, 2014). "This review summarizes the experimental data using rodent models on the effects of androgens in experimental breast cancer, aiming to highlight the role of androgens and androgen receptor (AR)-mediated androgen effects in experimental breast cancers." (PMID 25928046, 2014). "We examined androgen receptor protein expression by immunohistochemical analysis in 678 breast cancers, including 396 triple negative cancers." (PMID 24505496, 2014). "While ER, PR, and HER2 are oncogenic in breast cancer, another member of the steroid hormone receptor family, the androgen receptor (AR), has historically been considered anti-proliferative and beneficial." (PMID 25072326, 2014). "Further, several analyses based on unselected breast cancer cohorts showed that AR expression is related with ERα and PgR immunostaining as well as a marker of low grade differentiated disease." (PMID 24978437, 2014). "Our results with enzalutamide thus shed new light on the role of AR in breast cancer, since in vitro and in vivo preclinical studies demonstrate that inhibiting AR nuclear localization decreases both androgen and estrogen-stimulated tumor growth." (PMID 24451109, 2014). "We propose an explanation that reconciles conflicting reports regarding the role of AR in breast cancer by recognizing that hormonal influences on the breast are quite different in premenopausal versus postmenopausal women." (PMID 24451109, 2014). "The AR is the most prevalent sex steroid receptor occurring in up to 90% of breast cancers in early and metastatic setting and in a lower rate in TNBC (0–53%)." (PMID 24978437, 2014). "Both enzalutamide and bicalutamide inhibited 5-alpha-dihydrotestosterone (DHT)-mediated proliferation of breast cancer lines in vitro; however, enzalutamide uniquely inhibited estradiol (E2)-mediated proliferation of ER+/AR + breast cancer cells." (PMID 24451109, 2014). "The MDA-MB-453 breast cancer cell line represents the ER– molecular apocrine or luminal androgen receptor subtype of breast cancer with high levels of AR." (PMID 24451109, 2014). "The Oncomine mRNA data were confirmed by immunohistochemical analysis of AR expression on breast cancer TMAs obtained from two independent Institutional cohorts (OSU and RPCI)." (PMID 24505496, 2014). "Several studies in recent years highlighted the role of AR as independent prognostic factor for luminal breast cancer, confirming their tumor suppressive effect on ERα pathway." (PMID 24978437, 2014). "In this study, we investigated AR expression by immunohistochemical staining in 678 breast cancers, including 396 TNBCs." (PMID 24505496, 2014). "Many of the genes in the RRHGE gene signature are already defined as well-known oncogenes, such as AR, BRCA1, CDK2, and CCND1, besides others, whose differential expression has been associated with the subtypes of breast cancer." (PMID 24563630, 2014). "Both androgens exert their distinctive biological effects via the androgen receptor, which is coexpressed with estrogen receptor alpha in 80 to 90% of breast cancers." (PMID 25928046, 2014). "An association between AR expression and PIK3CA mutations was observed in a study which examined AR and ER expression and PIK3CA mutational status in 347 breast cancer patients." (PMID 25051360, 2014). "Breast cancer arrays containing cDNAs from 43 breast cancers and 5 normal breast tissues were probed for AR and its target gene, PSA." (PMID 25072326, 2014). "Metformin was found to inhibit EMT by interfering with TGF-β regulation in renal and in breast cancer cells and by modulating AR translation as shown herein and other EMT effectors such as MMP14." (PMID 24484909, 2014). "We estimated the frequencies of AR alleles to evaluate the association between AR-CAG repeats and breast cancer risk." (PMID 24581183, 2014).
breast carcinoma (continued). "We examined nuclear AR to ER protein ratios in primary breast cancers in relation to response to endocrine therapy." (PMID 24451109, 2014). "The MDA-kb2 cell line developed from MDA-MB-453 breast cancer cells endogenously expresses AR and has been stably transfected with the MMTV-luciferase plasmid." (PMID 25435875, 2014). "Its activation of the AR has been shown to play an important and major role in its antigonadotropic effects and in its beneficial effects against breast cancer." (PMID 25539790, 2014). "Nevertheless, most in vitro and in vivo studies indicate that activated AR exerts an anti-estrogenic, growth-inhibitory influence in ERα-positive luminal breast cancers, partly dependent on its ability to antagonize ERα signaling through several mechanisms." (PMID 24552459, 2014). "We estimated the frequencies of AR alleles and found that women with two long AR alleles (≥21 CAG repeats) had an increased risk of developing breast cancer, while those with two short AR alleles (<21 CAG repeats) were likely to be normal (p = 0.00069)." (PMID 24581183, 2014). "The androgen receptor (AR) is widely expressed in breast cancers and has been proposed as a therapeutic target in estrogen receptor alpha (ER) negative breast cancers that retain AR." (PMID 24451109, 2014). "We determined the expression of GCDFP-15 in breast cancer subtypes, its potential prognostic and predictive value, as well as its relationship to AR expression." (PMID 25070172, 2014). "To verify the high frequency of PIK3CA mutations in TNBC tumors with elevated levels of AR protein, we analyzed the RNA-seq, DNA-seq and reverse-phase protein array (RPPA) data in TCGA breast cancer cohort." (PMID 25103565, 2014). "A study conducted with 156 breast cancer samples to histologically determine AR and PSA expression showed that 72% of the samples expressed the two proteins with significant positive correlation between them." (PMID 25072326, 2014). "Overexpression of AR in MDA-MB436 breast cancer cells decreased L1CAM expression at the protein and mRNA level and CHIP-analysis revealed binding of AR to the L1CAM promoter region." (PMID 25510351, 2014). "The androgen receptor (AR) is the most highly expressed steroid receptor in breast cancer with 75–95% of estrogen receptor (ER)-positive and 40–70% of ER-negative breast cancers expressing AR." (PMID 25072326, 2014). "Tumoral LC3A expression was higher in AR-negative breast cancer, while tumoral BNIP3 was higher in AR-positive breast cancer." (PMID 25140630, 2014). "An ongoing clinical trial evaluating CDX as a single agent in metastatic AR+, ER-/PR- breast cancers (NCT00468715/TBCRC011) has demonstrated some efficacy with a clinical benefit rate of 19%." (PMID 25103565, 2014). "Before evaluating SARMs' growth inhibitory potential in breast cancer cells, we performed AR transactivation assays to determine if the SARMs are agonists in MDA-MB-231 cells." (PMID 25072326, 2014). "Collectively, these data provide evidence for a novel mechanism by which activated AR, through an up-regulation of ER-beta gene expression, inhibits breast cancer cell growth." (PMID 24552459, 2014). "AR is the most highly expressed receptor in breast cancer with more than 75–95% of ER-positive and 40–70% of ER-negative breast cancers expressing AR." (PMID 25072326, 2014). "AR-targeting has been introduced recently as a novel therapeutic option in TNBC, and a phase II trial of Bicatulamide (Casodex, AstraZeneca; nonsteroidal anti-androgen) treatment is ongoing in women with advanced AR+/ER−/PR− breast cancer." (PMID 24505496, 2014).
breast carcinoma (continued). "In order to understand the epithelial:MSC paracrine results and their correlation with AR function in breast cancer specimen, the expression of paracrine factors were correlated with PSA." (PMID 25072326, 2014). "There are emerging data regarding AR expression in breast cancers and the efficacy of hormone therapy, tamoxifen, and AIs." (PMID 24403250, 2013). "AR is expressed in the epithelium of the normal mammary gland and in approximately 70–90% of invasive breast cancers, a frequency comparable to that of ERα (70–80%) or PR (50–70%)." (PMID 23593223, 2013). "Androgen receptor (AR) is commonly expressed in both the epithelium of normal mammary glands and in breast cancers." (PMID 23593223, 2013). "We evaluated the expression of the androgen receptor (AR) to determine its significance in breast cancer." (PMID 24403250, 2013). "Clinically, a possible link has been established between AR expression and outcomes in certain subsets of breast cancer." (PMID 24324894, 2013). "Five articles reported the HR of AR expression in patients with ER positive breast cancer in text or table, while six articles reported the HR in patients with ER negative breast cancer." (PMID 24324816, 2013). "Peters and colleagues showed that the AR is a direct repressor of ERα signaling in breast cancer cells." (PMID 24403250, 2013). "Among nuclear receptors, the role of androgen receptor and estrogen receptor-α amplification and overexpression in prostate and breast cancer progression, respectively, is well known." (PMID 23907384, 2013). "All the included articles were on the association of AR expression with DFS and/or OS and covered a total of 5270 patients with breast cancer." (PMID 24324816, 2013). "The contribution of other signaling pathways has been nicely demonstrated in an ERα−/PR− breast cancer cell line engineered to express AR." (PMID 24324894, 2013). "The DFS of the patients with low-AR expression was worse, in spite of the use of adjuvant hormone therapy, compared to the prognosis of patients with high-AR breast cancer." (PMID 24403250, 2013). "Clinical data from 109 patients with breast cancer, who underwent surgery at Ruijin Hospital, Shanghai, were retrospectively analyzed for immunohistochemical AR expression measured by tissue microarray." (PMID 24324816, 2013). "Peters and colleagues demonstrated that the AR potently inhibited the transactivational activity of ERα and the 17β-estradiol–stimulated growth of breast cancer cells." (PMID 24403250, 2013). "Recent studies have highlighted the role of androgen receptor (AR) as a prognostic biomarker of breast cancer." (PMID 24324816, 2013). "In breast cancers, AR is overexpressed in up to 70% of cases, mainly in luminal and low grade tumors." (PMID 23663520, 2013). "AR, commonly expressed in breast cancer tissues, has been reported as a biomarker to understand the prognosis of breast cancer." (PMID 24324816, 2013). "For example, even though AR is frequently present in ERα+ breast cancers, AR has also been found in a significant percentage of ERα− tumors." (PMID 24324894, 2013). "The description of the MA breast cancer subgroup raises new questions about AR implication in prognosis or prediction of response to hormone blockade in an ER-negative setting." (PMID 23663520, 2013). "For meta-analysis, articles available in Pubmed on the relationship between AR and breast cancer outcomes were included." (PMID 24324816, 2013). "Some studies have examined and indicated that androgen acts through AR in carcinoma cells and play important roles in biology and clinical behavior of breast cancer model systems and cell lines." (PMID 24324816, 2013). "Several recent studies revealed that the AR is an independent prognostic factor for the outcome of ERα-positive breast cancer." (PMID 24403250, 2013). "AR has been an important target in prostate cancer, and it has recently been considered as a potential biomarker in breast cancer." (PMID 24324816, 2013).
breast carcinoma (continued). "We have previously demonstrated that the fatty acid metabolic enzyme, long chain fatty acyl-CoA synthetase 4 (ACSL4) is differentially expressed in human breast cancer samples as a function of expression of ER and AR." (PMID 24155918, 2013). "In the present study we demonstrate that in the MMTV-NeuNT mouse model of breast cancer the expression of AR in these tumors is reduced." (PMID 23593223, 2013). "The AR-mediated antiproliferative effects in breast cancer cells are influenced by the relative levels of endogenous AR and ERα." (PMID 24403250, 2013). "In this paper we report for the first time the case of a woman, with previous infertility, dramatic virilisation and chronic erythrocytosis, who was affected by an occult Leydig cell tumour and an androgen receptor positive breast cancer." (PMID 23816265, 2013). "This level of uncertainty and, perhaps, appreciation persists in spite of the apparent correlation between tumor cell expression of AR in the majority of human breast cancers and various features of the disease mentioned earlier in this paper." (PMID 24324894, 2013). "This set of experiments indicates that both mitogenic and migratory signaling of EGF requires AR/Src complex assembly in human prostate and mammary cancer-derived cells." (PMID 24130806, 2013). "Diminished expression of AR in the mammary glands of female mice leads to dramatically earlier onset of MMTV-NeuNT induced mammary tumors." (PMID 23593223, 2013). "The AR is the most prevalent sex steroid receptor in malignant breast tumors, and is expressed in up to 90% of primary tumors and 75% of metastasis." (PMID 24403250, 2013). "Using this system, we provide a mechanistic explanation for previous observations ascribing a dual role for AR signaling in human breast cancer cells." (PMID 22321971, 2012). "To delineate the key signaling pathways involved in the biology of molecular apocrine breast cancer, we have recently identified a positive feedback loop between the AR and extracellular signal-regulated kinase (ERK) signaling pathways in this disease." (PMID 22817771, 2012). "Positive AR immunostaining was found in approximately 70% of invasive female breast carcinomas and in a significant number of triple-negative tumors." (PMID 23273269, 2012). "Historically, side-effect profiles have limited the use of targeted AR therapies for breast cancer, but a more vexing problem has been the inability to predict response in pre-clinical models." (PMID 22321971, 2012). "This study highlights the potential for AR expression to be an informative prognostic biomarker for breast cancer survival and sets the scene for a more comprehensive investigation of the molecular basis of this phenomenon." (PMID 22471922, 2012). "It has also been shown that the assembly of the EGFR/AR/ER/Src signaling complex is crucial for proliferation of prostate and breast cancer cells triggered by androgens, estrogens and/or EGF." (PMID 22922989, 2012). "This study highlights the potential for AR expression to be an informative biomarker for breast cancer survival and sets the scene for a more comprehensive investigation of the molecular basis of this phenomenon." (PMID 22471922, 2012). "As mentioned, laboratory studies assessing the role of AR in breast cancer have been limited and conflicting." (PMID 22321971, 2012). "There were approximately two copies of AR for every two copies of chromosome X in primary breast cancer samples." (PMID 22321971, 2012). "Androgen receptors (AR) are frequently expressed in breast cancers, but their implication in cancer growth is still controversial." (PMID 23241075, 2012). "The significance of AR in human breast cancer is further emphasized by the recent finding that it can be targeted in estrogen receptor negative breast tumours." (PMID 22471922, 2012).
breast carcinoma (continued). "As previous reports have shown that approximately 40% of breast cancers can lack p21 expression, our data also identify potential new caveats for exploiting AR as a target for breast cancer therapy." (PMID 22321971, 2012). "T47D and MCF7 cells are two ER positive hormone-dependent breast cancer cell lines which additionally express AR." (PMID 22384035, 2012). "A recent study of case records for 1,849 patients with breast cancer revealed that positive AR immunostaining was inversely correlated with clinical stage, histological grade and mitotical score." (PMID 23273269, 2012). "Although published data support a significant biological role for the AR and ErbB2 signaling in molecular apocrine breast cancer, there is currently limited information regarding other functionally important genes and pathways in this disease." (PMID 22817771, 2012). "In part, this is due to the fact that most AR-positive breast cancer cell lines also express ERα and PR." (PMID 22321971, 2012). "In the present study, we further investigated the role of the androgen/AR pathway in breast cancer development." (PMID 23241075, 2012). "Understanding AR signaling in models of human breast cells that express AR exclusively would help to elucidate the role of AR in breast cancer and further the development of targeted therapies, particularly in the setting of ERα-negative disease." (PMID 22321971, 2012). "Among the top twelve genes in this ranking system, we have previously studied the transcriptional regulation of AR and ErbB2 in molecular apocrine breast cancer." (PMID 22817771, 2012). "This has recently spurred interest in AR as a potential breast cancer target for treating ERα-positive hormone-resistant breast cancers." (PMID 22321971, 2012). "A comparatively high expression of the androgen receptor (AR) within this subgroup of ER-negative samples (P = 4*10-44, t-test) suggested these cases to be of the apocrine breast cancer subtype." (PMID 22839103, 2012). "The role of elevated androgen levels and the AR expression in male breast cancer as well as in female breast cancer is still unclear." (PMID 23273269, 2012). "Because we have previously shown that hyperactivation of the EGFR pathway mimics oncogenic PIK3CA mutations, our results would suggest that breast cancers with mutant PIK3CA and AR expression would have a favorable therapeutic response to AR ligand binding." (PMID 22321971, 2012). "AR and ERα are co-expressed in most of the breast tumours and AR is emerging as an independent prognostic factor in ER+ breast cancer." (PMID 22343619, 2012). "Although a high frequency of androgen receptor (AR) expression in human breast cancers has been described, exploiting this knowledge for therapy has been challenging." (PMID 22321971, 2012). "Our results suggest that this combination therapy provides a promising therapeutic strategy in ER-/AR+ breast cancer." (PMID 21457548, 2011). "The AR-ERK feedback loop has potential therapeutic implications in molecular apocrine breast cancer." (PMID 21457548, 2011). "In this study, we investigated the therapeutic implications of the AR-ERK feedback loop in molecular apocrine breast cancer." (PMID 21457548, 2011). "In this study, we investigated the AR-ERK feedback loop as a therapeutic target in molecular apocrine breast cancer and demonstrated in vitro and in vivo synergies between AR and MEK inhibitors in this subtype." (PMID 21457548, 2011). "Molecular apocrine breast cancer constitutes approximately 50% of ER-tumors and is characterized by a steroid response gene signature that includes androgen receptor (AR) and a high frequency of ErbB2 overexpression." (PMID 21457548, 2011). "In our previous studies, we found that AR coactivator p44 plays an important role in both prostate and breast cancers, indicating involvement of the AR pathway in tumorigenesis of these endocrine organs." (PMID 22022581, 2011).